TCF4 (transcription factor 4)
Diseases named in the same sentence as TCF4 in open-access papers (continued):
Sharing a sentence is not in itself a finding about the gene and the disease.
multiple myeloma (5 papers, 2018 to 2026). "Using bioinformatic tools we found something interesting that in MMSA-1 promotor sequence, there may be binding site of transcription factor TCF4, which means MMSA-1 gene might be regulated by Wnt/β-catenin/TCF4 signaling pathway in myeloma cells." (PMID 41535418, 2026). "Others have reported that IL6 promoted the interaction of the TNIK/β-catenin/TCF4 complex (multiple myeloma cells:); transcriptional activity of the β-catenin/TCF4 complex is promoted by TNIK and inhibited by SF1, which induces an alternative splicing activity." (PMID 40003000, 2025). "Polymorphisms in genes involved in nervous system function, NFATC1, NFATC4, and EDN1 were associated with CIPN in 646 myeloma patients treated with bortezomib, as were TCF4, DYNC1I1, and GJE1 in 139 myeloma patients treated with bortezmib." (PMID 35360655, 2022). "Using CRISPR gene editing and/or the GO-203 inhibitor to silence MUC1 in multiple myeloma cells, MUC1-C was shown to activate MYC expression by binding to the promoter in a β-catenin/transcription factor 4-mediated mechanism." (PMID 29784646, 2018).
renal cell carcinoma (5 papers, 2010 to 2024). "Aberrant expression of TCF4 is associated with various forms of cancer, including renal cell carcinoma (RCC)." (PMID 20459685, 2010). "Importantly, research has demonstrated that β-catenin/TCF4-SCARA5 axis plays an important role in the progression of renal cell carcinoma (RCC)." (PMID 30249289, 2018).
viral infection (5 papers, 2018 to 2024). "While only local astrocytes were labeled in the WT neocortex, ectopic astrocytes were observed in the neocortex of Tcf4 cKO (Fig. EV4B), suggesting a fate transition occurred upon the loss of Tcf4 at the time of viral infection." (PMID 39300210, 2024). "The results showed that as the viral infection progressed, the expression of Wnt/β-catenin pathway-related genes β-catenin, TCF-4, LEF-1, c-Myc, and Cyclin D1 were significantly upregulated in RB1B infection group." (PMID 38638910, 2024). "We analyzed the densities of TCF4+YFP+ cells and found that they reduced to half from day 1 to day 2 after viral infection in Sox10+/rtTA mice at either P14 or P35." (PMID 34725188, 2021). "In addition, conditional ablation of Tcf4 was also reported to reduce pDCs numbers and ablate pDCs-driven IFN-I response upon viral infections." (PMID 30410494, 2018). "However, to exclude the possibility that viral infection itself might rescue behavioral phenotypes in PTHS model mice, we analyzed behavioral phenotypes from Tcf4+/+ and Tcf4STOP/+ mice after delivering AAV9/PHP.eB-hSyn-Green Fluorescence Protein (GFP) at P1." (PMID 35535852, 2022).
acute myeloid leukemia (4 papers, 2020 to 2025). Acute myeloid leukemia (AML) is a group of neoplasms arising from precursor cells committed to the myeloid cell-line differentiation. "In addition, it is also reported that TCF4 is highly expressed in hematopoietic stem cells, and is associated with the progression of myelodysplastic syndrome and acute myeloid leukemia." (PMID 32714094, 2020).
Alzheimer disease (4 papers, 2021 to 2025). A progressive, neurodegenerative disease characterized by loss of function and death of nerve cells in several areas of the brain leading to loss of cognitive function such as memory and language. "Additionally, the signatures of several transcription factors, such as Olig2, NeuroD1, TCF4, and NeuroG2, were found to be enriched in Alzheimer’s disease-associated accessible chromatin regions within hippocampal tissues." (PMID 40483385, 2025). "In the DisGeNET database, LRP6, F11, CXCL10, TCF4 and IGF2 are identified as the top five genes associated with Alzheimer's disease, with association scores of 0.989, 0.981, 0.953, 0.938 and 0.914, respectively." (PMID 38350848, 2024).
cervical cancer (4 papers, 2019 to 2025). A primary or metastatic malignant neoplasm involving the cervix. "In cervical cancer, TCF4 silencing suppresses proliferation and CSC characteristics by downregulating CD44 and Wnt/β-catenin pathway genes, such as β-catenin and c-Myc." (PMID 40290725, 2025). "For instance, in cervical cancer, NUSAP1 is shown to bound to the SUMO-E3 ligase Ran binding protein 2 (RanBP2) to induce the sumoylation of TCF4, thereby enhancing the Wnt/β signaling pathway and inducing tumor metastasis." (PMID 33927744, 2021). "NUSAP1 overexpression induced SUMOylation of TCF4 via binding NPC protein, RanBP2, is involved in the process of cervical cancer metastasis and progression." (PMID 30678687, 2019). "Our results also reveal that NUSAP1 increased the nuclear import of the TCF4 and β-catenin and their transcriptional activity via interacting with RanBP2 protein, and then enhanced CSCs properties and EMT processes in cervical cancer." (PMID 30678687, 2019). "Mechanistically, upregulation of NUSAP1 induced SUMOylation of TCF4 via interacting with SUMO E3 ligase Ran-binding protein 2 (RanBP2) and hyperactivated Wnt/β-catenin signaling in cervical cancer cells." (PMID 30678687, 2019). "Studies also showed that the over-expression of NUSAP1 stimulated sumoylation of TCF4 via interacting with SUMO E3 ligase Ran-binding protein 2 and hyperactivated Wnt/β-caternin signaling to induce cancer stem cell properties and EMT, and finally promoted the metastasis of cervical cancer." (PMID 31729978, 2019). "Moreover, NUSAP1 induced SUMOylation of TCF4 via interacting with SUMO E3 ligase Ran-binding protein 2 (RanBP2) and potently activated the Wnt/β-catenin signaling pathway, thus contributing to the metastatic and CSC-likeproperties of cervical cancer cells." (PMID 30678687, 2019).
colon adenocarcinoma (4 papers, 2008 to 2024). "Moreover, similar TCF4 silencing experiments performed in SW480 colon adenocarcinoma cells also decreased RHBG, Axin2 and Cyclin D1 mRNA levels." (PMID 26029888, 2015). "Therefore, our data are consistent with the activation of the Wnt/β-cat/Tcf-4 pathway in the development of colon adenocarcinomas." (PMID 18212756, 2008). "In contrast, colon adenocarcinoma showed a significant enrichment of TFs such as CDX2 (26.5%), CDX1 (24%), HOXA13 (22%), HNF4G (37.2%), and TCF4 (36%) in gained peaks; and FOS::JUNB (45.4%), FOS::JUND (47.5%) and JUNB (46.3%) in lost peaks." (PMID 34090364, 2021). "The results showed that the SNV frequencies of TCF4, TCF3, and TCF7 were highest in UCEC (42% for TCF4, 14% for TCF3 and TCF7), followed by skin cutaneous melanoma (SKCM) (38% for TCF4, 10% for TCF3, and 4% for TCF7) and colon adenocarcinoma (COAD) (13% for TCF4, 10% for TCF3, and 8% for TCF7)." (PMID 39205642, 2024).
colorectal adenoma (4 papers, 2008 to 2022). An adenoma that arises from the colon or rectum. "Over-expression of the CD44 family is an early event in the colorectal adenoma-carcinoma process, which suggests β-catenin/Tcf-4 signaling is crucial in initiating tumorigenesis." (PMID 21284870, 2011).
Crohn disease (4 papers, 2009 to 2023). A gastrointestinal disorder characterized by chronic inflammation involving all layers of the intestinal wall, noncaseating granulomas affecting the intestinal wall and regional lymph nodes, and transmural fibrosis. "For example, Crohn’s disease patients showed reduced HD5 and -6 levels, which were associated with decreased Tcf1, Tcf4, and LRP6, along with reduced Wnt signaling molecules Wnt1, -3, and -3a." (PMID 37762180, 2023).
esophageal cancer (4 papers, 2016 to 2025). A primary or metastatic malignant neoplasm involving the esophagus. "The expression of the TCF4/TCF7L2 protein in the nucleus of esophageal cancer cells was analyzed using immunohistochemistry." (PMID 28536608, 2016). "In this study, we found that increased expression of TCF4/TCF7L2 in the nucleus of cancer tissue cells was accompanied by the local progression of esophageal cancer." (PMID 28536608, 2016). "Downstream genes of the Wnt signal pathway in esophageal cancer may be activated by TCF4/TCF7L2 activation." (PMID 28536608, 2016). "Therefore, our data suggest that TCF4/TCF7L2 is involved in the cell proliferation of esophageal carcinoma and that TCF4/TCF7L2 is a useful biomarker for predicting prognosis in patients with ESCC." (PMID 28536608, 2016). "Because TCF4/TCF7L2 plays a role in cancer proliferation, additional studies are necessary to determine whether TCF4/TCF7L2 contributes to the growth of esophageal cancers." (PMID 28536608, 2016). "Although the precise molecular mechanisms through which TCF4/TCF7L2 is activated must be clarified, our data clearly indicate that TCF4/TCF7L2 may be a molecular target for the development of effective therapeutic agents for patients with esophageal cancer." (PMID 28536608, 2016). "Here, we investigated the clinicopathological significance of transcription factor 4/transcription factor 7-like 2 (TCF4/TCF7L2) in resectable esophageal squamous cell carcinoma (ESCC), because TCF4/TCF7L2 expression has not been studied in esophageal cancer previously." (PMID 28536608, 2016).
esophageal squamous cell carcinoma (4 papers, 2016 to 2025). Esophageal squamous cell carcinoma (ESCC) is a type of esophageal carcinoma (EC) that can affect any part of the esophagus, but is usually located in the upper or middle third. "The current study may be the first report demonstrating that TCF4/TCF7L2 is correlated with the prognosis of patients with esophageal squamous cell carcinoma." (PMID 28536608, 2016). "Interestingly, chromatin immunoprecipitation assays demonstrated the transactivation of HMGB1 mediated by a β-catenin/TCF4 complex, thus promoting DDR in esophageal squamous cell carcinoma (ESCC) consequent to exposure to ionizing radiation." (PMID 40001953, 2025).
Huntington disease (4 papers, 2020 to 2023). Huntington disease (HD) is a rare neurodegenerative disorder of the central nervous system characterized by unwanted choreatic movements, behavioral and psychiatric disturbances and dementia. "Past studies have noted that genes causing RTT-L are involved in neurodevelopmental diseases such as Dravet syndrome (SCN1A), Pitt–Hopkins syndrome (TCF4), and Huntington’s disease (HTT)." (PMID 37408271, 2023). "Expansion of the CTG18.1 locus in the TCF4 gene makes FECD one of the most common tri-nucleotide repeat disorders along with myotonic dystrophy (DM1 and DM2), Huntington disease (HD), Spinocerebellar ataxia (SCA), Friedreich ataxia (FA) and Fragile X syndrome (FRAXA)." (PMID 36773096, 2023).
lung adenocarcinoma (4 papers, 2013 to 2025). A carcinoma that arises from the lung and is characterized by the presence of malignant glandular epithelial cells. "In conclusion, this retrospective study underlines the previous results obtained in a mouse model concerning a role of LEF1/TCF4 in brain metastasis of lung adenocarcinoma." (PMID 23224985, 2013). "An essential function of the transcription factors LEF1/TCF4 in cerebral metastases of lung adenocarcinomas has been described in mouse models, while their clinical relevance in humans is still unclear." (PMID 23224985, 2013). "Nguyen and colleagues demonstrated an impact of a TCF4 as well as a WNT-lung signature on the relapse of patients with primary lung adenocarcinomas." (PMID 23224985, 2013). "An essential function of the transcription factors LEF1/TCF4 in cerebral metastases of lung adenocarcinomas has been described in mouse models, suggesting a WNT/β-catenin effect as potential mechanism." (PMID 23224985, 2013). "Additionally, we revealed the prognostic relevance of a LEF1/TCF4 signature in primary lung adenocarcinomas in a microarray dataset of primary lung adenocarcinomas." (PMID 23224985, 2013). "However, in another study, MPZL1 was found to inhibit the proliferation, metastasis, invasion, and cancer stem cell characteristics of lung adenocarcinoma by activating the β-catenin/TCF-4 signaling pathway, highlighting the complex role of MPZL1 in tumor development." (PMID 40223054, 2025). "Thus, in the present study, we focused on the role of WNT signaling in brain metastases of lung adenocarcinomas, investigating the expression patterns of LEF1, TCF4, and β-catenin in tissue samples of lung adenocarcinoma brain metastases and their impact on patient survival." (PMID 23224985, 2013). "Additionally, the cell-type-dependent effects of β-catenin and LEF1/TCF4 are underlined by our cluster analysis results based on the LEF1/TCF4 signature, in which the revealed clusters depicted diverging enrichment patterns of the cell cycle pathway in the primaries of lung adenocarcinomas." (PMID 23224985, 2013). "Furthermore, following a bioinformatics approach we generated a LEF1/TCF4 as well as an AXIN2 gene signature in cerebral metastases and investigated their prognostic value in a dataset of primary lung adenocarcinomas." (PMID 23224985, 2013). "In conclusion, our data show that LEF1/TCF4, but not β-catenin, have prognostic relevance in primary and cerebrally metastasized human lung adenocarcinomas." (PMID 23224985, 2013). "Our data indicate that LEF1/TCF4, but not β-catenin, have prognostic relevance in primary and cerebrally metastasized human lung adenocarcinoma patients." (PMID 23224985, 2013). "Additionally, we generated a LEF1/TCF4 as well as an AXIN2 signature, the latter as representative of WNT/β-catenin activity, following a bioinformatics approach with a gene expression dataset of cerebral metastases in lung adenocarcinoma." (PMID 23224985, 2013).
lymphoma (4 papers, 2012 to 2021). A malignant (clonal) proliferation of B- lymphocytes or T- lymphocytes which involves the lymph nodes, bone marrow and/or extranodal sites. "In a bortezomib-resistant lymphoma cell line, increased TCF4 expression and increased transcription by the TCF-4/β-catenin complex was observed, accompanied by upregulation of their downstream target genes (c-myc and cyclin D1)." (PMID 29765356, 2018).
acute lymphoblastic leukemia (3 papers, 2008 to 2018). Leukemia with an acute onset, characterized by the presence of lymphoblasts in the bone marrow and the peripheral blood. "JS-K could modulate the Wnt/β-catenin/TCF-4 signaling pathway in Jurkat T-acute lymphoblastic leukemia cells." (PMID 29986744, 2018).
atherosclerosis (3 papers, 2007 to 2024). A disease characterized by the build-up of fatty material and calcium deposition in the arterial wall resulting in partial or complete occlusion of the arterial lumen.
bladder cancer (3 papers, 2015 to 2022). "In bladder cancer cells LY294002, a PI3K inhibitor, inhibits phosphorylation of AKT and GSK3β, and ZEB1 expression due to inhibition of β-catenin/transcription factor 4 (TCF4) complex binding and transcriptional activity on ZEB1 promoter." (PMID 26098771, 2015).
clear cell renal cell carcinoma (3 papers, 2018 to 2025). "Although previous studies have shown that SPOP promotes tumor progression by activating the β-catenin/TCF4 complex in clear cell renal cell carcinoma, we found that SPOP inhibits CRC progression by degrading β-catenin." (PMID 41213915, 2025). "In clear cell renal cell carcinoma, SPOP drives EMT and promotes cell invasion via activation of β-catenin/TCF4 complex." (PMID 37382594, 2023).
corneal disease (3 papers, 2017 to 2023). "The TCF4 variant also strongly associates with CH and it is interesting to note that the TCF4 and ANAPC1 variants control almost the same quantitative corneal traits but have very different associations with corneal disease." (PMID 30894546, 2019). "We also found association of variants at known disease loci, TCF4 and CHST6 (FCED and MCD, respectively), with cell density and HEX, demonstrating how these structural measurements are affected by corneal diseases." (PMID 30894546, 2019).
heart failure (3 papers, 2022 to 2025). Inability of the heart to pump blood at an adequate rate to meet tissue metabolic requirements. "Furthermore, TCF4 OE could alleviate EndoMT and dysfunction of ECs derived from patients with hypertension-associated heart failure." (PMID 41160897, 2025). "Conversely, overexpression of TCF4 mitigates TGFβ-induced EndoMT and rescues the dysfunction of ECs from heart failure patients." (PMID 41160897, 2025). "Immunohistochemistry staining showed that TCF4 was significantly down-regulated in microvasculature ECs of heart failure patients, compared with normal donor controls." (PMID 41160897, 2025). "TCF7L2, also named TCF4, mediates canonic Wnt/β-Catenin signaling and c-Myc upregulation during abnormal cardiac remodeling in heart failure." (PMID 38373914, 2024). "We demonstrate that introducing exogenous TCF4 disrupts this TCF4–TGFβ feedback loop of EndoMT, rescuing the EC phenotype and function under TGFβ stimulation, as well as ECs from human patients with heart failure." (PMID 41160897, 2025). "To further test if exogenous TCF4 expression could mitigate EndoMT and EC dysfunction in heart failure patients, we isolated ECs from the tissue of heart failure patients." (PMID 41160897, 2025). "Notably, our results also demonstrated that exogenous TCF4 supplementation could disrupt this feedback loop, rescuing the phenotype and function of ECs under TGFβ stimulation, as well as ECs from heart failure patients." (PMID 41160897, 2025).
intestinal cancer (3 papers, 2013 to 2023). "However, some findings were conflicting, especially those that were related to the defects observed in the mouse gastrointestinal tract after Tcf4 gene deletion, or to a potential tumor suppressive role of the gene in intestinal cancer cells or tumors." (PMID 30200414, 2018). "It has been shown that c-Jun binds to TCF4 and β-catenin to promote intestinal cancer development." (PMID 23966864, 2013). "Further study revealed that Uhrf2 could bind and SUMOylate TCF4, an important transcription factor downstream of the Wnt signaling pathway, thus stabilizing TCF4 expression and activating Wnt signaling, and finally Uhrf2 promoted the progression of intestinal cancer." (PMID 37576596, 2023).
nasopharyngeal carcinoma (3 papers, 2019 to 2024). A carcinoma arising from the nasopharyngeal epithelium. "Interaction between MDSCs and nasopharyngeal carcinoma cells promotes TGFβ and nitric oxide (NO) production, which further upregulates COX‐2 expression subsequently activating MDSCs‐mediated EMT via the β‐catenin/TCF4 pathway." (PMID 38703051, 2024). "The interaction between MDSCs and tumor cells is mediated in part by cyclooxygenase‐2 (COX‐2) by activating the β‐catenin/TCF4 pathway, which suggests that inhibition of either COX‐2 or MDSCs may suppress metastasis of nasopharyngeal carcinoma." (PMID 38703051, 2024).
Obesity (3 papers, 2022 to 2025). Accumulation of substantial excess body fat. "Compared with the NC group, TCF4 was significantly more expressed in the obesity group and the obesity with the fracture group." (PMID 35401881, 2022). "The Obesity TRFs GATA2 and TCF4 were predicted to interact with four and two interactors, respectively." (PMID 40102990, 2025). "In the obesity signature, eight genes were found to possess regulatory functions: COPS5, GATA2, MORF4L1, OPTN, PFDN5, SETBP1, TCF4, and ZBTB16." (PMID 40102990, 2025).
renal fibrosis (3 papers, 2019 to 2025). A final common manifestation of a wide variety of chronic kidney diseases characterized by glomerulosclerosis and tubulointerstitial fibrosis. "In a streptozotocin-induced mouse model, activation of transcription factor 4 was shown to ameliorate renal fibrosis and reduce kidney injury by restoring autophagy." (PMID 40432887, 2025). "Moreover, TCF4 and MAFB, which are highly enriched in ECM_FIB, are associated with renal fibrosis and epithelial–mesenchymal transition, respectively." (PMID 38982264, 2024).